IRS1 (insulin receptor substrate 1)
Diseases named in the same sentence as IRS1 in open-access papers (continued):
Sharing a sentence is not in itself a finding about the gene and the disease.
Insulin resistance (continued). "Palmitic acid causes insulin resistance due to changes in the levels of phosphorylation of the IR and insulin receptor substrate-1 (IRS-1)." (PMID 26083118, 2015). "Not only mutations in exon of IRS1 are associated with diabetes, genetic variants (rs2943641; rs2943650) outside of IRS1 coding region are also though to be responsible for insulin resistance, hyperinsulinemia, dyslipidemia, and DM Type-2." (PMID 25978640, 2015). "TNF-α is an adipose tissue-derived proinflammatory cytokine that causes insulin resistance by enhancing adipocyte lipolysis and increasing the serine/threonine phosphorylation of IRS-1 (insulin receptor substrate-1)." (PMID 26136779, 2015). "Insulin resistance causes the impairment of IRS1 and GLUT4, which lead to obstacle of glucose utilization." (PMID 26843885, 2015). "ERK activation impairs IRS-1 activity and is associated with autophagy and ER stress-induced insulin resistance." (PMID 26697121, 2015). "Phosphorylation of Ser-312 causes IRS-1 proteasomal degradation that leads to insulin resistance under both pathological and physiological conditions, while phosphorylation of Ser-616 is supposed to inhibit insulin activation of PI3-kinase." (PMID 25580119, 2014). "Chronic increased mTORC1 activity causes insulin resistance through inhibition of the insulin receptor substrate 1 (IRS-1; Howell & Manning, 2011)." (PMID 24408966, 2014). "We investigated the independent and joint effects of PPARG Pro12Ala and IRS1 Gly972Arg on markers of insulin resistance and T2DM in an African population with elevated risk of T2DM." (PMID 24447396, 2014). "The PPARG Pro12 is associated with insulin resistance and this polymorphism interacts with IRS1 Gly972Arg, to increase the risk of T2DM in the mixed-ancestry population of South Africa." (PMID 24447396, 2014). "Insulin resistance is thus associated with reduced responses to insulin signaling in the IR/IRS-1/PI3K and greatly with IGF1 in the IGF1R/IRS-2/PI3K signaling pathways." (PMID 25346723, 2014). "In conclusion, the PPARG Pro12 is associated with insulin resistance and this polymorphism interacts with an additional unfavourable genetic polymorphism, IRS1 Gly972Arg, to increase the risk of type 2 diabetes in the mixed ancestry population of South Africa." (PMID 24447396, 2014). "The peroxisome proliferator-activated receptor gamma (PPARG) and the insulin receptor substrate (IRS1) genes have been shown to be associated with both insulin resistance and type 2 diabetes." (PMID 24447396, 2014). "In contrast, the glycine to arginine substitution in codon 972 (Gly972Arg) of the IRS1 gene is associated with an increased risk of insulin resistance." (PMID 24447396, 2014). "Although IrsLDKO mice are only deficient in hepatic Irs1 and Irs2, they manifest systemic insulin resistance as well, which is indicated by decreased phosphorylation of Akt and Erk in the skeletal muscle." (PMID 23940800, 2013). "The phosphorylation of JNK mediates in turn the phosphorylation of IRS1 (insulin-receptor substrate 1) on serine residues which is known to inhibit phosphorylation of IRS1 on tyrosine residues causing insulin resistance." (PMID 23741455, 2013). "IRS-1-deficient mice showed a phenotype of peripheral insulin resistance (mainly in muscle and white adipose tissue)." (PMID 23533500, 2013). "TNF-α has been implicated in the progression of insulin resistance; it disrupts phosphorylation of several proteins involved in insulin-signalling pathway, including IRS1, tyrosine, and most importantly, the downregulation of glucose transporter 4 (GLUT4)." (PMID 24391675, 2013). "Mouse genetic data have shown that deletion of Irs1 and Irs2 genes in the mouse liver (IrsLDKO) causes severe insulin resistance and early onset of diabetes." (PMID 23940800, 2013).
Insulin resistance (continued). "Subsequent analyses showed that MC4R rs17782312, involved in weight regulation, and IRS1 rs2943634, related to insulin resistance were associated with MetS (OR 1.16, 95%CI 1.02-1.32 and OR 0.88, 95% CI 0.79; 0.97, respectively)." (PMID 23101478, 2012). "JNK can cause insulin resistance through the phosphorylation of serine residues in insulin receptor substrate-1 (IRS-1)." (PMID 22792473, 2012). "Insulin resistance in this model was due to lipid-induced defects in the insulin signaling pathway that was caused by a reduction in tyrosine phosphorylation of IRS1, increasing its phosphorylation in serine-307 residue." (PMID 22360800, 2012). "In genome-wide scans to date, the majority of the genetic variants for type 2 diabetes identified in European-derived populations appeared to be related to impaired insulin secretion, while only IRS1 has been unequivocally associated with insulin resistance." (PMID 22438884, 2012). "Of the five insulin resistance SNPs included in the group IRS1 rs2943634 was the only SNP individually associated with MetS or MetS-score." (PMID 23101478, 2012). "Recent genome-wide association studies with human T2D patients have identified a genetic variant near the IRS1 gene associated with decreased IRS1 levels, increased T2D, insulin resistance and hyperinsulinemia." (PMID 22859932, 2012). "Out of the group of five insulin resistance SNPs, IRS1 rs2943634 was the only SNP significantly associated with MetS and MetS score." (PMID 23101478, 2012). "Recently, a GWAS of type 2 diabetes identified a type 2 diabetes risk variant (rs2943641, near IRS1) that was associated with insulin resistance and hyperinsulinemia in populations of European ancestry." (PMID 21747906, 2011). "HFD-induced insulin resistance also caused a decrease in IR and IRS-1 protein in muscle by 60% and 64%, respectively and a reduction of IR protein in fat by 48%, whereas AKT protein levels were increased upon HFD feeding." (PMID 21731668, 2011). "Another example is inhibitor kappaB kinase (IKK), which contributes to insulin resistance by phosphorylating protein IRS-1, a protein that has been annotated to be associated with insulin pathway." (PMID 21738677, 2011). "In conclusion, we have demonstrated that mitochondrial dysfunction induced by mtDNA depletion or metabolic inhibition causes the development of insulin resistance in hepatocytes through a reduction in the expression of IRS-1." (PMID 21464990, 2011). "SFAs inhibit the activation of insulin receptor substrate 1, which causes insulin resistance and contributes to metabolic syndrome." (PMID 21829457, 2011). "Taken together, these data clearly indicate that the induction of miR-126 causes insulin resistance in hepatocytes through a reduction in the expression of IRS-1." (PMID 21464990, 2011). "Hepatic insulin resistance is caused by alterations in substrate 1 (IRS-1) and substrate 2 (IRS-2) of the insulin receptor." (PMID 20946638, 2010). "In a related study, obesity-induced stress was shown to cause insulin resistance via JNK-mediated phosphorylation of inhibitory serine residues IRS-1." (PMID 20508722, 2010). "IRS-1 in endothelial cells and fat cells can be downregulated by stressors like hyperglycemia and dyslipidemia, causing insulin resistance and endothelial dysfunction." (PMID 20634940, 2010). "The principal mechanism by which JNK causes insulin resistance is through the phosphorylation of serine residues in insulin receptor substrate-1 (IRS-1)." (PMID 20508722, 2010). "Elevations in phosphorylation at both IRS-1 sites, Ser312 and Ser636/639, have been reported in other studies in association with insulin resistance." (PMID 19169352, 2009). "There are other factors causing insulin resistance, known to be involved in elevated IRS-1 serine phosphorylation including tumor necrosis factor α (TNF-α), free fatty acids, cellular stress, amino acids, and insulin." (PMID 19169352, 2009).
Insulin resistance (continued). "In contrast to Irs-1-/- mice, Irs-2-deficient mice develop early-onset diabetes due to a combination of peripheral insulin resistance and a loss of β-cell function." (PMID 19534786, 2009). "The current study reports a link between a hyperinsulinemic/hyperandrogenic environment and an elevation in serine phosphorylation of IRS-1, which has been associated with insulin resistance." (PMID 19169352, 2009). "Previous studies suggested other pathways such as the mitogen activated protein kinase (MAPK) pathway and the stress activated protein kinase JNK, which are implicated in insulin induced IRS-1 serine phosphorylation and insulin resistance." (PMID 19169352, 2009). "Although in the present study we cannot determine which component (serine phosphorylation of IRS-1 or increased expression of p85α) plays a greater role, these changes are typically associated with insulin resistance in skeletal muscle." (PMID 19781106, 2009). "Several polymorphisms of IRS1 and IRS2 genes (IRS1 andIRS2) have been implicated in insulin resistance." (PMID 17389770, 2007). "Insulin resistance is associated with decreased IRS‐1 and Glut 2 protein expression in the liver." (PMID 41065424, 2025). "Indeed, we observed a decrease in IRβ and its substrate IRS-1 in the db/db mice, associated with insulin resistance, that was restored by further loss of NEDD4-2." (PMID 40617804, 2025). "Further mechanistic studies reveal that lactylation promotes IRS-1 serine 636 phosphorylation in skeletal muscle cells—a phenomenon directly linked to impaired insulin signaling cascades—thereby reinforcing its role in insulin resistance." (PMID 41393289, 2025). "At 2 years of follow-up, the effect of the CC genotype on changes in insulin and HOMA-IR remained significant in the highest-carbohydrate-diet group, demonstrating that the IRS1 variant rs2943641 may improve insulin resistance in response to weight-loss diets." (PMID 40732974, 2025). "Thus, higher IRS-1 Ser-307 phosphorylation has been linked to insulin resistance, but its “cause and effect” relationship needs more investigation." (PMID 40141412, 2025). "Furthermore, we observed decreased levels of IRS-1 in db/db livers, which is associated with aldosterone-induced insulin resistance." (PMID 40617804, 2025). "For example, pro-inflammatory cytokines, such as TNF - α, cause insulin resistance by promoting adipocyte catabolism and increasing serine/threonine phosphorylation of insulin receptor substrate-1 (IRS-1) through a variety of signalling pathways, including the IKKβ/NF-κB pathway." (PMID 40084146, 2025). "GK rats show (i) an impaired glucose metabolism under the IPGTT underlying a state of insulin resistance, (ii) a consistently impaired insulin signaling activation in the brain, characterized by IRS1 hyper-activation but reduced downstream effects, and (iii) impaired cognitive functions." (PMID 38843768, 2024). "Besides directly inhibiting IRS-1, the underlying mechanism of insulin resistance by inflammatory mediators occurs through the activation of NF-κB, and inhibitor of nuclear factor kappa B kinase subunit β (IKKβ)." (PMID 39728000, 2024). "Finally, another insulin resistance type has been identified at the central level in obese subjects and individuals with the G972R polymorphism in IRS-1, which is associated with T2DM and peripheral insulin resistance." (PMID 38612888, 2024). "TNF-α, a crucial contributor to insulin resistance, suppresses the activity of insulin receptor tyrosine kinase and causes the phosphorylation of insulin receptor substrate 1, weakening insulin signaling, which in turn triggers metabolic disorders associated with obesity." (PMID 39116149, 2024). "Besides, the over activation of JNK during sustained ERS promotes serine phosphorylation and inhibits tyrosine phosphorylation of IRS-1, which consequently causes inhibition of insulin receptor signaling and insulin resistance." (PMID 40302954, 2024).
Insulin resistance (continued). "Further, the effects of similar diets are not limited to peripheral changes but are also associated with central insulin resistance, as evidenced through the increased serine phosphorylation of IRS-1 and inflammatory responses through nuclear factor kappa beta (NFKβ) and JNK activity." (PMID 38257161, 2024). "Furthermore, several IRS1 polymorphisms have been shown to be associated with insulin resistance and GDM in some populations." (PMID 39684804, 2024). "The abnormal phosphorylation of IRS-1 has also been associated with brain insulin resistance." (PMID 38255204, 2024). "IRS1-deficient mice have mild glucose intolerance and insulin resistance." (PMID 38397596, 2024). "Post-binding steps in insulin signaling, such as reduced TK activity, a decreased expression of insulin receptor substrate-1 (IRS-1), and increased levels of the p85α subunit of PI 3-kinase, are mainly involved as causes of insulin resistance in women with gestational diabetes mellitus." (PMID 38539988, 2024). "This suggests that peripheral hyperglycemia, hyperlipidemia, and insulin resistance may be associated with decreased activity of central IRS-1 and P-AKT proteins." (PMID 38283741, 2023). "One possible explanation is that the destruction of substrate IRS1/2 will cause insulin resistance." (PMID 36982617, 2023). "Also, an induction of IRS1 has been shown by others, too, to be associated with the development of insulin resistance in diet-induced MASLD." (PMID 37683301, 2023). "Therefore, Mrap, Gpd1, Irs1 and Myc appear to play key roles in transmitting the Pparg signal to promote the AT expansion and concomitant insulin resistance in females, upon the loss of ovarian function." (PMID 36768630, 2023). "This indicates that IRS1/2 is the cause of selective insulin resistance; in some cases, the insulin signal transduction in the liver remains intact, but the involuntary cellular pathway may be blocked resulting in an increase in HGP during insulin resistance." (PMID 36982617, 2023). "APMAP caused insulin resistance through IRS-1/insulin sensitive genes/free fatty acids pathway." (PMID 36766716, 2023). "Human placental lactogen (hPL) causes insulin resistance via decreasing phosphorylation of IRS-1." (PMID 36631877, 2023). "A state of hyperuricemia may lead to a reduction in IRS1 activity, thus causing a state of insulin resistance." (PMID 37760978, 2023). "Since Ser307 phosphorylation of IRS-1 is linked to cytokine-mediated insulin resistance, it may explain the blunted effect of insulin on Akt phosphorylation and on the reduction in FFA release in OSM-treated adipocytes." (PMID 35531859, 2022). "They suggested that IRS1 rs2943641 variants are associated with insulin resistance and are modulated by diet, so they may have important functions in various metabolic disorders, and dietary factors may modify these correlations." (PMID 36009479, 2022). "Interestingly, the abnormal function of IRS1 protein is involved in the development of insulin resistance, and the loss of IRS proteins is suggested to be a link between diabetes and cardiac insulin resistance in HF." (PMID 35101146, 2022). "Notably, IRS-1-deficient mice show a phenotype of peripheral insulin resistance (mainly in muscle and white adipose tissue)." (PMID 35320949, 2022). "In particular, IRS-1 serine phosphorylation leads to increased levels of free fatty acids, diacylglycerol, fatty acyl-CoA, ceramides, and glucose, leading to obesity-associated insulin resistance." (PMID 35625904, 2022). "Furthermore, accumulating recent evidence has suggested that certain microRNAs (miRNAs) dysregulated in obesity are causally linked to hepatic insulin resistance by targeting IRS-1." (PMID 35328400, 2022). "miR200c downregulates IRS1, which is associated with insulin resistance." (PMID 39086962, 2022). "Inflammatory mediators are also associated with non-IRS-1 related insulin resistance." (PMID 35327570, 2022).
Insulin resistance (continued). "Likewise, overexpression of PDGF increased the risk for T2DM, hyperglycemia, as well as insulin resistance by decreasing the insulin receptor and insulin receptor substrate 1 (IRS-1) protein abundance." (PMID 36292250, 2022). "Aβ was further shown to potentiate the TNF-α/PICR-dependent activation of PKR, another IRS-1 Ser-kinase in neurons, to drive IRS-1 phosphorylation and insulin resistance as well as ER stress-associated eIF2α induction and subsequent synaptic damage, LTP impairment and memory deficits in vivo." (PMID 36117625, 2022). "Insulin resistance could be caused by inhibition of insulin receptor substrate-1 (IRS-1), and it could impair glucose transporter 2 (GLUT2) translocation in hepatocytes." (PMID 34684533, 2021). "Importantly, IRS1 polymorphism is significant genetic determinant for insulin resistance and obesity in OSA and NAFLD." (PMID 34449768, 2021). "Moreover, detection of IRS1 novel variants that substantially contribute to the development of insulin resistance needs to be assessed." (PMID 34445300, 2021). "The obtained data shows that β-Caryophyllene treatment is beneficial for decreasing the progression & risk of insulin resistance and type-2 diabetes by increasing the IR, IRS-1 Akt and GLUT 4 expression in the skeletal muscle of high fat diet andfructose-induced type-2 diabetic rats." (PMID 35540699, 2021). "Therefore, the aim of our study was to evaluate changes of the glycemic profile parameters and insulin resistance in type 2 diabetic patients with comorbid obesity and chronic pancreatitis considering the allele status of the IRS1 polymorphism rs2943640." (PMID 35221617, 2021). "MDP-stimulated insulin resistance was associated with increased inhibitory serine phosphorylation of insulin receptor substrate-1 (IRS-1) and reduced activating IRS-1 tyrosine phosphorylation, as well as decreased GLUT4 translocation and insulin-stimulated glucose uptake." (PMID 33503814, 2021). "In addition to its association with type II diabetes and insulin resistance, IRS1 also promotes tumorigenesis by regulating the ErbB-PI3K-AKT signaling cascade." (PMID 34805171, 2021). "All these data lend support to the notion that differential hepatic distribution of Irs1/Irs2 could be one of the mechanisms underlying the selective insulin resistance observed in MAFLD." (PMID 33923817, 2021). "Furthermore, genetic deletion of IRS1/2 in mice exhibiting liver mitochondrial dysfunction, which underlined the direct association between insulin resistance and mitochondrial dysfunction." (PMID 34603021, 2021). "IRS1-deficient mice showed normal glucose tolerance and insulin resistance." (PMID 34966805, 2021). "In addition, IRS1 is associated with type II diabetes, susceptibility to insulin resistance and tumorigenesis." (PMID 34805171, 2021). "Interestingly, our study also indicated that IRS1 polymorphism is significant genetic determinant for insulin resistance in OSA and NAFLD." (PMID 34449768, 2021). "The activated JNK causes insulin resistance in obesity and possibly in diabesity in four ways: inhibition of IRS-1 phosphorylation directly, the inhibition of PPARα-FGF21 axis hormones, induction of cytokines and inflammation, and enhanced metabolic and adipogenesis efficiency." (PMID 33995826, 2021). "Interestingly, cognitive disorders found in the AD brain were associated with brain insulin resistance linked to increased serine phosphorylation of IRS-1." (PMID 33931731, 2021). "Certain type 2 diabetes risk alleles associated with insulin resistance secondary to a metabolically unfavourable lipodystrophy-like fat distribution (e.g. IRS1) are associated with lower birthweight but those implicated in obesity or liver lipid metabolism are not." (PMID 33569631, 2021). "Basic research suggested that IRS-1 serine phosphorylation was linked to insulin resistance." (PMID 32453705, 2020).